BRCA2 (BRCA2 DNA repair associated)
Diseases named in the same sentence as BRCA2 in open-access papers (continued):
Sharing a sentence is not in itself a finding about the gene and the disease.
breast cancer (continued). "Previously, we and others showed that most breast tumors arising in PALB2 mutation carriers are ER+, PR+, and HER2-, like both BRCA2-related and sporadic breast cancer." (PMID 18053174, 2007). "In a retrospective cohort study of 1,601 female BRCA1 and BRCA2 mutation carriers we found an association with reported chest X-ray exposure and significantly increased risk of breast cancer (hazard ratio 1.54)." (PMID 17428320, 2007). "All families had at least three individuals diagnosed with breast cancer in first-degree relatives and presence of the BRCA2-8765delAG mutation in all family probands from the three populations was confirmed by direct sequencing." (PMID 17640379, 2007). "The BRCA2-8765delAG mutation was firstly described in breast cancer families from French-Canadian and Jewish-Yemenite populations; it was then reported as a founder mutation in Sardinian families." (PMID 17640379, 2007). "BRCA2, since its discovery as a breast cancer susceptibility gene, has been implicated in processes fundamental to all cells, including proliferation, development, DNA repair, transcription, and centrosome duplication." (PMID 17945002, 2007). "It is interesting to presume that the low-penetrating SNP can modulate the fine-tuned regulation of the multifunctional gene BRCA2, leading to the differential form of genomic instability and rendering risk to the sporadic form of breast cancer." (PMID 17945002, 2007). "Germline mutations in the high-penetrance genes BRCA1 and BRCA2 account for up to 25% of the hereditary forms of breast cancer (BC)." (PMID 17504528, 2007). "Three of the five BRCA2 mutation carriers previously affected by contralateral breast cancer were found to have aberrant methylation in DL samples from their healthy breasts." (PMID 17324252, 2007). "BRCA2 carriers had a breast cancer risk of 84% (95% CI 43–95%), and an ovarian cancer risk of 27% (95% CI, 0–47%)." (PMID 17213823, 2007). "Similar results were reported for BRCA1 and BRCA2 mutations in Korean women with breast cancer at a young age (< 40 years) and also for BRCA1 mutations in a series of Singaporean Chinese women with early onset (cut-off of 40 years)." (PMID 18053234, 2007). "In the Breast Cancer Linkage Consortium cohort of 173 breast and/or ovarian cancer families, a RR of 4.7 (95%CI 3.5–6.2) was reported for prostate cancer among BRCA2 protein-truncating mutation carriers." (PMID 17700570, 2007). "Mutations in high-penetrant genes such as BRCA1 (breast cancer 1, early onset) and BRCA2 account for only a small proportion of this hereditary component, suggesting an important but yet-to-be-detected role for low-penetrant single nucleotide polymorphisms." (PMID 17598882, 2007). "Cancer risks were similar in BRCA1 and BRCA2 carriers, and by age 70 years breast cancer risk was 56% (95% CI 40–73%), and ovarian cancer risk was 16% (95% CI 6–28%)." (PMID 17213823, 2007). "Study on BRCA1 and BRCA2 mutations in Saudi women older than 40 years with breast cancer concluded that mutations in these genes are likely to contribute to the pathogenesis of familial breast cancer in the Kingdom of Saudi Arabia." (PMID 18053234, 2007). "There are also reports of mutations in BRCA1 and BRCA2, which affect familial breast cancer occurrence, though their penetrance is low." (PMID 17919326, 2007). "The recurrent BRCA2 mutation occurred in 1 of 60 (1.7%) women diagnosed with breast cancer before 41 years of age and one of 80 (1.3%) women with ovarian cancer." (PMID 16539696, 2006). "Women with a known family history of breast and/or ovarian cancer or mutations in BRCA1 and BRCA2 have a higher lifetime risk of breast cancer than the general population with tumours often occurring at a young age and more often being of a high grade." (PMID 17016484, 2006).
breast cancer (continued). "In our survey, all MBC patients carrying deleterious BRCA2 mutations had a family history of breast cancer." (PMID 16764716, 2006). "We investigated the distribution and the nature of BRCA1 and BRCA2 germline mutations and polymorphisms in a cohort of 204 Indian breast cancer patients and 140 age-matched controls." (PMID 17018160, 2006). "Although carried out on a limited series, the present study confirms that BRCA2 mutations are associated with a significant fraction of breast cancer cases in men." (PMID 16764716, 2006). "BRCA1 and BRCA2 are considered to be the breast cancer genes, but BRCA1 is also associated with ovarian cancer." (PMID 16721370, 2006). "When only the 23 families segregating the BRCA2 founder mutation 8765delAG were used, the cumulative breast cancer risk by age 70 was estimated to be 71% and the corresponding ovarian cancer cumulative risk to be 51%." (PMID 16417652, 2006). "A number of studies have suggested mutations of CDKN2A and BRCA2 as possible determinants of the higher incidence of melanoma among breast cancer patients." (PMID 17024122, 2006). "In BRCA1 or BRCA2 mutation positive families, the highest risk quintile included almost all the women that developed breast cancer over the comparatively short period of four years of follow-up." (PMID 16507150, 2006). "The authors found a 50% increased risk of breast cancer among women with a BRCA2 mutation who had 2 or more children (OR 1.53; 95% CI = 1.01 to 2.32; p = 0.05)." (PMID 16563180, 2006). "Genistein caused dose- and time-dependent increases in BRCA1 and BRCA2 protein levels in two oestrogen-responsive breast cancer cell lines (MCF-7 and T47D)." (PMID 16434996, 2006). "We found two genes associated with breast cancer, BRCA2 and ERBB2, in which the chimpanzee sequence differed from the human in residues that have been reported to be polymorphic in humans." (PMID 16438707, 2006). "Mutations in BRCA1 and BRCA2 are present in only 35% to 40% of concentrated family clusters of breast/ovarian cancer; hence it is likely that other 'high-penetrance' breast cancer susceptibility genes remain to be identified." (PMID 16507150, 2006). "The results from this study suggest a reduction in the risk of breast cancer in BRCA2 mutation carriers with a history of interrupted pregnancies." (PMID 16563180, 2006). "We show that epithelial proliferation in breast tissue from women with BRCA1 and BRCA2 mutations or who are otherwise at high risk is stimulated by oestradiol to the same extent to that in tissue taken from women at population risk of breast cancer." (PMID 16538216, 2006). "In this report we have used data from 810 BRCA1 and BRCA2 mutation carriers from the UK to assess the effect of parity on breast cancer risk." (PMID 17187672, 2006). "The lifetime breast cancer risk for BRCA2 mutation carriers approaches that of BRCA1 carriers: however, disease onset has been documented to be at a later age." (PMID 17018160, 2006). "Germline mutations in one allele of the BRCA1 or BRCA2 genes significantly increase the risk of developing early-onset breast cancer." (PMID 16846527, 2006). "BRCA1 and BRCA2 mutations appear to account for a lower proportion of breast cancer patients at increased risk of harboring such mutations in Northern India (6/204, 2.9%) than has been reported in other populations." (PMID 17018160, 2006). "Parous BRCA1 and BRCA2 mutation carriers were at a significantly lower risk of developing breast cancer (hazard ratio 0.54, 95% confidence interval 0.37 to 0.81; p = 0.002)." (PMID 17187672, 2006). "In the four BRCA2 mutation carrier families, breast cancer was more frequent in the first and second-degree relatives than in the five w.t. families." (PMID 16764716, 2006). "Carriers of mutations in the BRCA1 and BRCA2 genes have up to a 90% lifetime risk of developing breast cancer and effective preventative strategies are required for these women." (PMID 16538216, 2006).
breast cancer (continued). "The main focus behind the study is to provide reliable hospital based estimates of genetic influence, and to characterize the nature and prevalence of BRCA1 and BRCA2 germline mutations in early-onset and familial breast cancer cases." (PMID 17018160, 2006). "About 6% of breast cancer cases in women < 50 years of age are due to germline mutations in the BRCA1 or BRCA2 breast and ovarian cancer susceptibility genes." (PMID 16800895, 2006). "A protective effect of incomplete pregnancies among BRCA2 mutation carriers remained when we assessed the relationship between the total number of spontaneous and therapeutic abortions and breast cancer risk." (PMID 16563180, 2006). "A large number of distinct mutations in the BRCA1 and BRCA2 genes have been reported worldwide, but little is known regarding the role of these inherited susceptibility genes in breast cancer risk among Indian women." (PMID 17018160, 2006). "Treatment guidelines of breast cancer occurring in BRCA1/BRCA2 mutation carriers or in patients with an increased familial risk are not well established." (PMID 16404417, 2006). "We used retrospective data on BRCA1 and BRCA2 mutation carriers from the UK to assess the effects of parity-related variables on breast cancer risk." (PMID 17187672, 2006). "Available evidence indicates that BRCA2 mutation carriers have an increased risk of breast cancer in both males and females, as well as of prostate and pancreatic carcinomas." (PMID 16764716, 2006). "In our series, the high prevalence of BRCA2 mutation (about 40%) correlated with the high number of relatives with breast cancer present in these families." (PMID 16764716, 2006). "A similar proportion of breast cancer families, especially those that include one or more cases of male breast cancer, is linked to a second locus (BRCA2) on chromosome 13." (PMID 16507150, 2006). "To date, only few studies have attempted to estimate the risk of breast cancer in male carriers of a BRCA2 mutation." (PMID 16764716, 2006). "As did Andrieu and colleagues, we found a significant association for breast cancer risk and pregnancy at older ages among BRCA2 mutation carriers." (PMID 17187672, 2006). "In families with BRCA2 mutations, female breast cancer was more frequent in the first and second-degree relatives compared to the families with wild type BRCA1/2 (31.9% vs. 8.0% p = 0.001)." (PMID 16764716, 2006). "The prevalence of the BRCA1 or BRCA2 mutation found in this study among women with breast cancer and a family history of breast cancer was 13% (4/31)." (PMID 16389418, 2005). "Our analyses provide no support for an association between AR CAG repeat length and breast cancer risk in either BRCA1 or BRCA2 mutation carriers." (PMID 15743497, 2005). "The BRCA1 or BRCA2 mutation prevalence found among women with breast cancer and such family history was 13% (4/31)." (PMID 16389418, 2005). "In the case of BRCA2-associated breast cancers, it appears that loss of heterozygosity (LOH) occurs as a means of silencing the second allele." (PMID 16280055, 2005). "BRCA2-associated cancers were diagnosed at younger age (median age 47 years) than unselected breast cancers (median age 56 years, P ≤ 0.0005)." (PMID 15642173, 2005). "The objective was to detect BRCA1 and BRCA2 mutations in Brazilian patients with breast cancer, so as to establish genetic profiles." (PMID 16389418, 2005). "A 52 years old paternal cousin (III-3), also affected with breast cancer, was previously identified as a BRCA2 mutation carrier at another institution." (PMID 16079000, 2005). "Protein-truncating mutations of BRCA2 are usually deleterious and increase the risk of breast cancer up to 80% over a lifetime." (PMID 16280055, 2005). "The overall odds ratio for breast cancer in women with a single copy of the BRCA2 C5972T variant was 1.1 (p = 0.7); however, the effect was significant for patients diagnosed at or before age 40 (OR = 1.4; p = 0.04)." (PMID 16280055, 2005).
breast cancer (continued). "The identification of BRCA1 and BRCA2 mutations is relevant for establishing preventive strategies for women with breast cancer and BRCA mutations, in order to prevent contralateral breast tumors and ovarian tumors." (PMID 16389418, 2005). "Early reports of The Breast Cancer Linkage Consortium estimated a contralateral breast cancer cumulative risk of 50–60% at age 70 years in BRCA1 or BRCA2 mutation carriers." (PMID 16052221, 2005). "Mutations in the two high penetrance genes BRCA1 and BRCA2 are well known, but they account for only 20–30% of the familial aggregation of breast cancer." (PMID 15987455, 2005). "The first breast cancer case was diagnosed at the age of 28 years in the BRCA2 mutation carrier who presented with a palpable axillary mass at 27 months post-SCM." (PMID 16079000, 2005). "A literature review using PubMed, searching from 1994 to the present, revealed this to be the first reported case of breast cancer occurring post-SCM in a carrier of a BRCA2 gene mutation." (PMID 16079000, 2005). "Our data show that CPM markedly reduces the risk of contralateral breast cancer among BRCA1 or BRCA2 mutation carriers with a history of breast cancer." (PMID 16052221, 2005). "The C5972T allele of the BRCA2 gene appears to be over-represented in women with early onset breast cancer in Poland compared to controls." (PMID 16280055, 2005). "It is likely that more prevalent low-penetrance genes in combination with environmental exposures modify breast cancer risk in BRCA1 and BRCA2 mutation carriers as well as contribute to breast cancer risk among women in the general population." (PMID 15756256, 2005). "In summary, women with a BRCA1 or BRCA2 gene mutation and a history of unilateral invasive breast cancer are at increased risk for developing a primary contralateral breast cancer." (PMID 16052221, 2005). "The aim of this study was to detect BRCA1 and BRCA2 mutations in a group of Brazilian patients with breast cancer, in an attempt to establish a genetic profile for this population." (PMID 16389418, 2005). "Women with a BRCA1 or BRCA2 mutation and a personal history of breast cancer have high risks of developing contralateral breast cancer." (PMID 16052221, 2005). "Accounting for some 15% of all cases, BRCA2 mutations are the most common heritable factors in male breast cancer, and, in addition to breast cancer, carriers have an increased risk of prostate, pancreatic and stomach cancers and melanomas." (PMID 15798766, 2005). "This is the first study to investigate BRCA1 and BRCA2 mutations among Brazilian patients with breast cancer." (PMID 16389418, 2005). "We have also documented previously that efficient predictors for BRCA1 and BRCA2 mutations are early age of breast cancer onset and number of ovarian cancer cases in the family." (PMID 15987451, 2005). "We report an unusual case of late occurrence of breast cancer after SCM in a BRCA2 mutation carrier." (PMID 16079000, 2005). "A large number of distinct mutations, polymorphisms and genetic variants of uncertain significance in the BRCA1 and BRCA2 genes is described in the Breast Cancer Information Core Database (BIC Database)." (PMID 16168118, 2005). "The BRCA2 mutations were detected in two patients who developed the disease before the age of 45 years and who have at least two second-degree relatives with breast carcinoma." (PMID 16389418, 2005). "Because some studies suggest that the CHEK2 1100delC variant acts as a breast cancer modifier in non-BRCA1/BRCA2 families only, we considered the subset of women known not to be BRCA1 or BRCA2 germline mutation carriers." (PMID 15535844, 2004). "It has been found that this procedure reduces the risk of ovarian cancer by 96% and breast cancer by 53% in BRCA1 or BRCA2 mutation carriers." (PMID 15083174, 2004).
breast cancer (continued). "About 5–10% are the so-called familial cases, which can be mainly attributed to deleterious mutations in BRCA1 and BRCA2, and also for the remaining majority of spontaneous breast cancer cases a strong genetic component has been postulated." (PMID 15138483, 2004). "Male breast cancer in combination with a family history of breast/ovarian cancer was indicative of finding a BRCA2 mutation (P=0.002), which is consistent with a recent population-based British study." (PMID 15026808, 2004). "BRCA1- and BRCA2-associated breast cancer tumours have also been reported to have different pathological characteristics from one another, and also from sporadic and other familial tumours." (PMID 15381934, 2004). "Epidemiological studies have demonstrated that BRCA1 and BRCA2 mutations account for less than 20% of the familial aggregation of breast cancer." (PMID 15381934, 2004). "Patient III: 17 was only tested for three markers, but the result is consistent with the presence of a BRCA2 mutation and she was diagnosed with breast cancer at age 33 years." (PMID 14735197, 2004). "This resulted in somewhat higher predicted prevalence for BRCA2 mutations among unselected breast cancer patients." (PMID 15381934, 2004). "The pattern of predicted age-specific contributions of BRCA1 and BRCA2 mutations to breast cancer is generally in line with the results of the population studies, where the contribution is highest at young ages at onset and thereafter it decreases." (PMID 15381934, 2004). "Three mutations (BRCA1 IVS5+3A>G, 2626–2627delAA and BRCA2 6503–6504delTT) were found in 41 sporadic patients with early-onset breast cancer and one mutation (BRCA1 E1221X) in two sporadic patients diagnosed with both breast and ovarian cancer." (PMID 15026808, 2004). "In this paper, we have examined the frequencies of the BRCA1 and BRCA2 mutations in unselected series of breast cancer patients, and the FRRs of breast cancer, predicted by the BOADICEA model, since these can be compared with empirical observations." (PMID 15381934, 2004). "As an example, mutations in the BRCA1 and BRCA2 genes account for around 2%–3% of all breast cancer cases, although more prevalent founder mutations in these genes can explain up to about 10% of the disease in some populations." (PMID 15630470, 2004). "A single-nucleotide polymorphism (SNP), RAD51-135g → c, in the 5′ untranslated region of the gene has been found to elevate breast cancer (BC) risk among BRCA2 carriers." (PMID 15138485, 2004). "Although we did not investigate BRCA gene mutations in all patients in the present study, we performed BRCA1 and BRCA2 gene mutation scanning in 22 patients who had two or more breast cancer patients in their 1st degree relatives." (PMID 15546499, 2004). "In case of the 372H allele (BRCA2), an increased risk for developing breast cancer has been observed together with an association with foetal survival." (PMID 15138483, 2004). "Up to 15–30% of women aged less than 35 years diagnosed with breast cancer are likely to have germ-line BRCA1 or BRCA2 mutations." (PMID 15546499, 2004). "For affected males (all with BRCA2 mutations), mean age at diagnosis of breast cancer was 59.4 years (95% CI 51.9–67.0)." (PMID 12698193, 2003). "In Iceland, only one mutation has been found in each of the BRCA genes, a rare BRCA1 mutation, D1692N (<1% of breast cancer cases) and a more common BRCA2 mutation." (PMID 12644832, 2003). "BRCA1 and BRCA2 are breast cancer susceptibility genes: inheritance of one defective copy of either of the two genes predisposes individuals to breast, ovarian and other cancers." (PMID 12838319, 2003). "Perhaps reflecting this, there is some evidence of BRCA1 and BRCA2 mutation carriers having a lower apoptotic response than other breast cancer patients." (PMID 12592359, 2003).